IRS2 (insulin receptor substrate 2)
Diseases named in the same sentence as IRS2 in open-access papers (continued):
Sharing a sentence is not in itself a finding about the gene and the disease.
Insulin resistance (continued). "Notably, new-onset hyperglycemia has been associated with SARS-CoV-2 because non-diabetic COVID-19 patients were found to have increased risk of insulin resistance, which may be associated with Mpro cleavage of IRS2." (PMID 37670988, 2023). "Moreover, our results suggested that TAC-induced impairment of hepatic insulin signaling (manifested as decreased levels of GLUT2, IRS2 and pAKT) might cause the insulin resistance observed in patients with NODAT." (PMID 37151651, 2023). "Gly1057Asp inside IRS2 has been linked to greater insulin resistance and T2D in obese Caucasian youngsters, Kurdish ethnics, Iranians, and Asian Indians, while research in a Turkish women's population suggests that this genetic variation may be linked to GDM as well." (PMID 36589630, 2022). "Together these studies reveal an important role for macrophage Irs2 in systemic metabolism and reveal new details of the signaling mechanisms underlying the cross-talk between the immune and nervous system relevant to the pathogenesis of obesity and insulin resistance." (PMID 30553769, 2019). "Upon completion of the proposed research project, a sub-set of SNPs in genes encoding the IRS-1, IRS-2, glucose transporters, pro- and anti-inflammatory genes will be identified in Dahl S rats that might likely influence their susceptibility to insulin resistance and salt-sensitive hypertension." (PMID 18570670, 2008). "Similarly, mutations or defects in IRS2 may lead to insulin resistance and metabolic disorders." (PMID 40747301, 2025). "It has been shown that there is an increased SOCS-1 expression in insulin-sensitive tissues in obesity and that this inhibits the phosphorylation of IRS-1 and IRS-2, leading to the inhibition of downstream signaling and insulin resistance." (PMID 40572705, 2025). "In IRS1- or IRS2-knockout mice, the peripheral tissues of the mice exhibit insulin resistance due to the blockage of PI3K/AKT signaling, and the impairment of insulin secretion further contributes to the development of diabetes mellitus." (PMID 40747301, 2025). "In hepatocytes, ATF3 represses the ChREBP-Scd1 axis, indirectly preserving IRS2 function and glucose homeostasis by reducing lipid-induced insulin resistance." (PMID 40747301, 2025). "In mHypoE-46 neurons, treatment with 10nM insulin for 6 hours, which is prior to the development of cellular insulin resistance, still resulted in significant downregulation of Igf1r, Irs1, and Irs2." (PMID 40105689, 2025). "Fe deposition in the liver leads to oxidative stress disorders, increases apoptosis, decreases the expression of IRS2 and GIUT2 in the liver, causes insulin resistance, and eventually leads to abnormal glucose metabolism." (PMID 40082989, 2025). "Further regulatory network analysis revealed that insulin resistance and sensitivity pathways were modulated through key genes, including IRS2, CPE, ADRB2, NR4A3, and FGF19." (PMID 40969325, 2025). "In the pancreas, vaspin upregulates IRS-2 expression, thereby promoting β-cell proliferation and alleviating insulin resistance." (PMID 41463050, 2025). "GKB extract increases pancreatic β-cell function and improves insulin sensitivity by enhancing IRS-2 transcription, as IRS-2 is a crucial element in insulin signaling, and studies have found that a deficiency of IRS-2 causes insulin resistance." (PMID 40150513, 2025). "In IRS2 knockout mice, male mice are normal in body size but develop diabetes at approximately 8 weeks of age due to hepatic and peripheral insulin resistance and pancreatic β-cell insufficiency." (PMID 40747301, 2025). "PC in H-Exo also activates AhR in adipocytes and skeletal muscle cells, inhibiting the expression of IRS-2 and further exacerbating insulin resistance." (PMID 40129979, 2025). "Excess glucose and fructose metabolism, via activation of ChREBP, contributes to IRS-2 down-regulation, hyperinsulinemia reinforces it, and together they drive development of hepatic insulin resistance and MASLD." (PMID 41196673, 2025).
Insulin resistance (continued). "Glucose and glycolysis have a principal role in β-cell proliferation, and glucokinase-induced IRS2 is involved in compensatory β-cell proliferation in response to high-fat, diet-promoted insulin resistance." (PMID 38201998, 2024). "It is known that activation of inflammatory pathways via serine kinase phosphorylation of IRS1 and IRS2 establishes a link between inflammation and insulin resistance." (PMID 39268230, 2024). "Other studies showed that srebp-1c in the liver represses insulin receptor substrate-2 (IRS-2) transcription by displacing forkhead proteins from the insulin response element on the IRS-2 promoter, contributing to hepatic insulin resistance." (PMID 39519478, 2024). "For example, liver-specific Irs1/Irs2 double-knockout mice show insulin resistance in adipose tissue, which is relieved when hepatic FoxO1 is deleted." (PMID 38967989, 2024). "Since SREBP-1c is regulated by insulin receptor substrate 2 (IRS-2), in states of insulin resistance, IRS-2 is down-regulated." (PMID 38612556, 2024). "Key findings include the disruption of insulin signaling pathways due to aberrant phosphorylation of IRS-1 and IRS-2, resulting in impaired glucose uptake and insulin resistance." (PMID 39519193, 2024). "This is consistent with the results of previous studies showing IRS2 involvement in insulin resistance–responsive compensatory β-cell proliferation." (PMID 38201998, 2024). "Ubiquitin-mediated degradation of IRS1 and IRS2 is another mechanism which promote cytokine induced insulin resistance and have contribution in diabetes as well as in β cells dysfunctioning." (PMID 37014444, 2023). "BBR can improve insulin resistance by upregulating insulin receptor substrate-2 (IRS-2) and down regulating UCP2 at the mRNA and protein levels along with a decrease in TC, TG, and LDL-C and an increase in HDL-C in HFD-induced NAFLD model rats." (PMID 38034996, 2023). "Cyclin D2 drives β cell compensation in response to insulin resistance, but islet cyclin D2 levels are reduced in Irs2–/– mice; rescue by Cdk4-R24C makes sense in this context." (PMID 37712417, 2023). "Mice with knocked-out IRS-1 and IRS-2 genes in the liver exhibited significant signs of hyperglycemia, hyperinsulinemia, hyperlipidemia, and insulin resistance." (PMID 37108143, 2023). "Disruption of hepatic insulin signalling induces NAFLD and hepatic insulin resistance through insulin receptor substrate-2 gene deletion, leading to upregulation of SREBP-1, leading to the development of obesity, diabetes and NAFLD in laboratory animals." (PMID 37360298, 2023). "We also reduced the expression of IRS2 in wild type mice liver to examine its role in Dex-induced insulin resistance." (PMID 37253782, 2023). "Earlier studies have recorded that the deterioration of glucose homeostasis due to IRS-2 and PI3K deficiencies led to insulin resistance in the liver." (PMID 36977005, 2023). "Many investigations have shown that defects in the insulin signaling pathway, especially those associated with insulin receptor substrate-2 (IRS-2), are definitely implicated in the pathogenesis of insulin resistance." (PMID 37895151, 2023). "The impairment of the insulin signal and insulin resistance was further confirmed in our NAFLD model by a significant decrease in the hepatic expression of IRS-2." (PMID 37261280, 2023). "BrdU incorporation was only significantly increased by Cdk4-R24C in the Irs2–/– context, suggesting the proliferation was amplified by insulin resistance." (PMID 37712417, 2023). "Although Ehmt2K182R/K182R mice had worsened insulin sensitivity compared to WT mice upon Dex treatment, overexpression of Irs2 in the liver of Ehmt2K182R/K182R mice significantly ameliorated glucose intolerance and insulin resistance in Dex-treated mice." (PMID 37253782, 2023). "Initially, TAC was observed to induce hepatic insulin resistance, impair IRS2/AKT signaling, and upregulate PINK1/Parkin in mice." (PMID 37151651, 2023).
Insulin resistance (continued). "Here were found many genes whose expression positively correlates with obesity, insulin resistance, type-2 diabetes and chronic inflammation, such as Irs2, Angptl4, Lepr, Camkk2 and Tbk1." (PMID 37957359, 2023). "Our study confirmed that HFD induces an increase in body weight, hyperglycemia and insulin resistance in APP/PS1 mice accompanied by the downregulation of IRS2 protein levels in the liver, a protein involved in insulin signaling regulation." (PMID 36895036, 2023). "When hepatocytes are re-fed, SREBP-1c can seize the binding site between TFE3/FOXO1 and IRS-2, inhibiting the expression of IRS-2 and causing hepatic cell insulin resistance." (PMID 36906611, 2023). "For example,Tumor necrosis alpha (TNF-α) directly causes insulin resistance through insulin receptor substrate-1 (IRS-1) and insulin receptor substrate-2 (IRS-2 via promoting serine/threonine phosphorylation of the substrates." (PMID 35401518, 2022). "IRS-1 and IRS-2 are downstream signal factors of InsR, and those are the critical kinase of glucose uptake and the target of insulin resistance." (PMID 35845787, 2022). "Other genes upregulated were BCL2A1, an anti-apoptotic player, usually implicated in cancer progression, as well as YWHAZ, YWHAH, and IRS2, which participates in the development of insulin resistance as well as hepatocellular carcinoma." (PMID 36612019, 2022). "IRS-1 and IRS-2 regulate insulin-dependent hepatic glucose metabolism, and their dysregulation contributes to insulin resistance and type 2 diabetes." (PMID 36290594, 2022). "Insulin receptor substrates include insulin receptor substrate-1 (Irs1) and insulin receptor substrate-2 (Irs2), and Irs1 and Irs2 double knockout mice developed liver insulin resistance, which resulted in hyperinsulinemia and diabetes." (PMID 35242879, 2022). "In mice, conditional knockout of Irs2 led to increased appetite and insulin resistance that progressed to diabetes and lower levels of thyroid hormones." (PMID 35945490, 2022). "For example, knockout of neuronal Irs2 early in brain development extends lifespan and improves hippocampal function, despite resulting in weight gain and insulin resistance." (PMID 35707855, 2022). "It is important to mention that a decrease in IRS1 and IRS2 with an accompanying activation in Foxo1 is also present in the heart of animals with DM type 2 or insulin resistance." (PMID 35454166, 2022). "Hepatic insulin resistance state and impairment in insulin signaling were additionally confirmed in our MS model by a remarkable reduction in the hepatic expression of IRS-2." (PMID 35990819, 2022). "Animal studies have shown an increased appetite, lean and fat body mass, linear growth, and insulin resistance that progressed to diabetes when Irs2 was conditionally knocked out in the pancreas β cells and the hypothalamus of mice." (PMID 36297523, 2022). "It has been proposed that decreased tyrosine phosphorylation of IRS-1 and increased phosphorylation of IRS-2 Ser 312 are the molecular mechanisms of insulin resistance among PCOS patients." (PMID 35327342, 2022). "IRS1 and IRS2 are vital components of insulin signaling, and the loss of IRS1 and IRS2 mediates insulin resistance." (PMID 35454166, 2022). "It has been reported that SOCS-1 and SOCS3 are associated with insulin resistance in various cells through degradation of IRS-1 and IRS-2." (PMID 34416903, 2021). "Further, in vitro experiments using MIN6 cells showed that AOS regulated INS-R, IRS-1, IRS-2, and Glut4 protein and mRNA levels and attenuated insulin resistance and cell apoptosis." (PMID 34497509, 2021). "IL-1α and IL-1β have been reported to impair insulin signaling by altering tyrosine phosphorylation of insulin receptor substrate (IRS-1 and IRS-2), which leads to insulin resistance." (PMID 33924165, 2021).
Insulin resistance (continued). "Treatment of Eugenol, an aromatic oil extracted from cloves, activated insulin receptor substrate-2 (IRS-2) to improve IR evidenced by reducing Homeostasis model assessment for insulin resistance (HOMA-IR) and hepatic triglycerides." (PMID 34299189, 2021). "In mice liver, miR-33 regulates the expression of insulin receptor substrate 2 (IRS2), that is related with insulin resistance." (PMID 33668203, 2021). "First, we provide new evidence for the increased serine phosphorylation levels of IRS1 (Ser307) and IRS2 (Ser731) as molecular mechanism of insulin resistance observed in the bladder mucosa of FFRs." (PMID 33859259, 2021). "Intraventricular injection of Aβ induces brain insulin resistance, as evidenced by hyperphosphorylation of IRS2 and AKT." (PMID 34485269, 2021). "These events prevent serine kinase phosphorylation of IRS-1/IRS-2 and thus protect the cells from insulin resistance." (PMID 33917607, 2021). "CR has been shown to improve insulin resistance in mice through hypermethylation and downregulation of Srebp1 as well as through hypomethylation and upregulation of Irs2, the direct target of SREBP1." (PMID 33193730, 2020). "IRS2 dysregulation is responsible for the phenomenon of selective insulin resistance that is observed in type 2 diabetes." (PMID 32710190, 2020). "-Inhibition of miR-122 via inhibition of JNK pathway and restoring the function of IRS1/IRS2 and insulin signaling. -Abrogated the insulin resistance observed in mice under high fat diet." (PMID 33585535, 2020). "Sterol regulatory element-binding protein 1 (SREBP1) contributes to insulin resistance by interfering with the binding of FOXO1 to the insulin receptor substrate 2 (Irs2) promoter, thereby repressing Irs2 expression." (PMID 33193730, 2020). "Under pathophysiological conditions including obesity and insulin resistance, selective endothelial insulin resistance is promoted by proteasomal degradation of IRS-2." (PMID 32610588, 2020). "It has been reported that the organ responsible for insulin resistance in IRS2-/- mice is the liver." (PMID 33270683, 2020). "We previously proposed that IRS1 is more critical than IRS2 in insulin resistance–metabolic syndrome of the NTS." (PMID 32532282, 2020). "In livers of FFC + E- and FFC + B-fed mice, expressions of insulin receptor (Insr) and insulin receptor substrate 2 (Irs2), shown to be indicative of hepatic insulin resistance, were significantly higher than in those of C-D-fed mice (P ≤ 0.05)." (PMID 30879098, 2020). "Here, we report that SHP2 knockdown enhances glucose consumption, ameliorates insulin resistance, activates IRS‐2 and AKT, and inhibits ERK1/2 phosphorylation in liver." (PMID 33012117, 2020). "We concluded that mice from the EPA lineage exhibited an improved response against fat accumulation, insulin resistance through a regulatory axis involving Pgc-1α, Irs2, and miR-34a-5p." (PMID 33348802, 2020). "More importantly, the IRS2/AKT pathway was critical for liver insulin signaling to regulate insulin resistance in muscle and liver of diabetic rats." (PMID 32169080, 2020). "Estradiol levels were lower andglucose blood levels and insulin resistance were higher in Sham operated (Sham) males compared to Sham females.Irs2, Pik3cd, and Esr1/2 mRNA levels were lower in the liver of Sham males than in Sham females." (PMID 33659826, 2020). "In order to further investigate the therapeutic effect of MNAM on insulin resistance, we examined protein expression and phosphorylation levels of IRS2, PI3K, AKT, and GSK3β, part of the hepatocyte insulin signaling pathway, by Western blot." (PMID 32280711, 2020). "Since the liver is one of the primary target organs of insulin action, levels of key proteins involved in insulin signaling pathway including InsR, IRS2, and phospho-Akt were detected to investigate insulin resistance in all experimental groups." (PMID 32132984, 2020).
Insulin resistance (continued). "Our data and bioinformatics analysis suggested a contribution of insulin receptor substrate 2 (Irs2) in the effect of Pgc-1α against insulin resistance." (PMID 33348802, 2020). "So far, multiple studies have demonstrated the ability of metformin to activate the hepatic insulin receptor and the IRS2/PI3K/Akt pathway resulting in reduced insulin resistance and increased glucose uptake." (PMID 32780768, 2020). "Some studies have found upregulated expression of IRS1, IRS2 in PCOS patients, and the circulating Leptin levels have been directly correlated with insulin resistance, which frequently is associated with PCOS." (PMID 32038578, 2019). "PTPN1 found from the network study is linked to the common network pathway and modulates insulin resistance through Jak-Stat, insulin receptor substrates (IRS1 and IRS2) and leptin signaling pathway." (PMID 30674322, 2019). "For example, TNF-α over expression with obesity signals through IκB kinase β to phosphorylate IRS-1 and IRS-2 to promote insulin resistance, which in turn promotes liver TG accumulation." (PMID 30730895, 2019). "The association between insulin resistance and DRs has been demonstrated in liver disorders including NASH and chronic hepatitis C, in which defective IRS2 expression has also been reported." (PMID 30695023, 2019). "This is supported by previous results obtained in ir/irs-2+/− transgenic mice, which developed insulin resistance in the liver and skeletal muscle and modest β-cell hyperplasia." (PMID 30360437, 2018). "Examination of the KEGG pathway for NAFLD (hsa04932) demonstrated transcriptional dysregulation of mediators of insulin resistance (IRS2, P1K3R1, AKT1), steatohepatitis ( JUN, ERN1) and neutrophil infiltration and inflammation (CXCL8)." (PMID 29786565, 2018). "On the other hand, mice lacking 3-phosphoinositide-dependent protein kinase 1 (PDK1) in the myeloid cells, which are downstream signaling molecules in the IR/Irs2 pathway, showed adipose tissue inflammation and insulin resistance under the HF diet condition." (PMID 30451856, 2018). "Both systemic IRS1 null mice and IRS2 null mice displayed insulin resistance, indicating both are irreplaceable." (PMID 30602666, 2018). "It has been suggested that chronic hyperinsulinemia activates p38 (p38α MAPK mitogen-activated protein kinase) which can reduce IRS1 and IRS2 proteins by promoting their ubiquitination and/or degradation, resulting in insulin resistance." (PMID 30602666, 2018). "PKCε activation participates in the pathogenesis of lipid-induced insulin resistance through defecting insulin-stimulated IRS-2 tyrosine phosphorylation." (PMID 29700319, 2018). "And 5-PAHSA treatment decreased IRS2 phosphorylation at Ser731, which related with insulin resistance." (PMID 30666198, 2018). "During preparation of this manuscript, it was reported that hepatic IRS-2 knockout mice develop selective insulin resistance." (PMID 29717275, 2018). "Dysfunction of IRS1 and IRS2 in different tissues contributes local, or even systemic insulin resistance, and pathogenesis of metabolic diseases." (PMID 30602666, 2018). "The pathology of hyperinsulinemia-induced insulin resistance is associated with impaired Ser/Tyr phosphorylation of IRS-1 and IRS-2 that impairs their interactions with cytoplasmic domain of insulin receptors and deregulate the insulin signaling." (PMID 29786669, 2018). "Insulin receptor substrates 1 and 2 (IRS1 and IRS2) predominantly mediate insulin signaling in the liver, and liver-specific IRS1- or IRS2-knockout mice exhibit insulin resistance in distinct ways." (PMID 29749571, 2018). "In this study, we found that in obesity, the hyperinsulinemia presumably downregulates MΦ Irs2 expression, resulting in impaired IL-4-induced M2a-subtype MΦ activation, and consequently, development of inflammation and insulin resistance in the liver and WAT." (PMID 30451856, 2018).